JAK2 (Janus kinase 2)
Diseases named in the same sentence as JAK2 in open-access papers (continued):
Sharing a sentence is not in itself a finding about the gene and the disease.
osteoporosis (8 papers, 2017 to 2025). A condition of reduced bone mass, with decreased cortical thickness and a decrease in the number and size of the trabeculae of cancellous bone (but normal chemical composition), resulting in increased fracture incidence. "The associations among SOCS1, AGO3, and the JAK2/STAT3 signaling pathway in osteoporosis progression were then evaluated." (PMID 41043430, 2025). "Other studies showed that RANKL expression in osteoblasts is promoted by activators of the transcription 3 (STAT3) pathway and Janus kinase 2 (JAK2) signal transducers, which induces the differentiation of BMSCs into osteoclasts, leading to osteoporosis." (PMID 37175732, 2023). "A number of traditional Chinese medicines inhibit osteoporosis through the JAK2/STAT3 pathway." (PMID 35879773, 2022). "However, recent studies have demonstrated that the activation of JAK2/STAT3 signalling is increased by some miRNAs regulation in osteoporosis samples; for example, miR-151a-3p and miR-125b." (PMID 35879773, 2022). "This suggested that the related target molecules had an important role in GCK-treated osteoporosis, especially for the targets STAT3, PIK3R1, VEGFA, JAK2 and MAP2K1." (PMID 36430397, 2022).
Parkinson disease (8 papers, 2015 to 2025). A progressive degenerative disorder of the central nervous system characterized by loss of dopamine producing neurons in the substantia nigra and the presence of Lewy bodies in the substantia nigra and locus coeruleus. "In a Parkinson’s disease rat model, inhibitors of JAK1 and JAK2, such as AZD1480, reduced microglial proliferation and macrophage infiltration and decreased MHC class II expression." (PMID 39229261, 2024). "Conversely, numerous studies indicate that the activation of JAK2/STAT3 inhibits the onset of Alzheimer’s, Parkinson’s, and myocardial-cerebral vascular diseases." (PMID 38794201, 2024).
Portal vein thrombosis (8 papers, 2011 to 2024). Thrombosis of the portal vein and/or its tributaries, which include the splenic vein and the superior and inferior mesenteric veins. "Rao and Grosel reported a similar case of portal vein thrombosis in a 59-year-old patient with JAK2 V167F mutation." (PMID 39877786, 2024).
renal carcinoma (8 papers, 2010 to 2024). A carcinoma arising from the epithelium of the renal parenchyma or the renal pelvis. "To date, there is no data on the effects of simvastatin on regulating IL-6-induced JAK2/STAT3 signaling in renal cancer cells." (PMID 23690956, 2013). "Moreover, isoliquiritigenin inhibited the JAK2 and STAT-3-associated apoptosis in human renal carcinoma." (PMID 39574470, 2024). "One small-molecule STAT3 inhibitor, AG490, was originally selected from a group of tyrphostins screened for their ability to block Jak2 activity and has been shown to inhibit growth and induce apoptosis in some types of cancer cells, including renal cancer cells." (PMID 20461084, 2010). "On the other hand, the pre-treatment of simvastatin inhibited phosphorylation of JAK2 and ERK1/2 in renal cancer cells upon IL-6 stimulation." (PMID 35955474, 2022). "Similar to TDEs, renal cancer TDE-anchored IL-12 (EXO/IL-12) also provides a much smaller reduction in p-STAT5 expression but has the same inhibitory effect on JAK3, but not on JAK2." (PMID 37514090, 2023).
T-cell lymphomas (8 papers, 2012 to 2026). "Finally, treatment with ruxolitinib, the kinase inhibitor preferentially impairing activity JAK1 and JAK2, showed therapeutic efficacy against diverse T-cell lymphomas, particularly the ones with evidence of JAK/STAT mutations or even STAT3 activation, foremost in T-LGL." (PMID 38638855, 2024). "However, PCM1::JAK2 fusion is rarely observed in other lymphoproliferative malignancies (such as T-cell lymphomas)." (PMID 41530508, 2026). "In turn, cytotoxic CD8+ T-cell lymphomas of skin, particularly the primary cutaneous, aggressive and epidermotropic cytotoxic T-cell lymphoma (PCAECyTCL) show alterations of predominantly JAK2 but also JAK3, STAT5B, and SOCS1 genes, among other genomic changes." (PMID 38638855, 2024). "Studies showing JAK2 aberrations in T-cell lymphomas are limited." (PMID 29262599, 2017).
thromboses (8 papers, 2014 to 2025). "When thromboses occur in children, they can be severe, particularly in the presence of JAK2 V617F mutations or hyperviscosity symptoms." (PMID 41552126, 2025). "Initiating the prospective trial “Prevalence of JAK2 mutations in patients with abdominal venous thromboses” was a step toward distributing highly sophisticated diagnostic tools to potentially all patients in MV." (PMID 38274463, 2023). "Thrombotic disorders commonly involved mutations in PROC (27%), PROS1 (12%), SERPINC1 (9%), ADAMTS13 (5%), and JAK2 (3%)." (PMID 40488813, 2025). "The number of major thromboses at or prior to diagnosis was significantly higher in JAK2 patients (n = 149, 23%) compared to CALR (n = 16, 9%; p < 0.001) and TN (n = 11, 10%; p = 0.003)." (PMID 38238287, 2024). "Consistent with the literature, individuals with abdominal venous thromboses and JAK2 p.V617F were more likely to be female." (PMID 38274463, 2023). "In conclusion, controlling platelets and inflammation with hydroxyurea and aspirin may help improve the condition in case of rapid thrombosis due to the JAK2 V617F mutation, unlike other thromboses." (PMID 38021556, 2023). "Collectively, these findings indicate that JAK2 hyper-activation can promote CVD by altering hematopoiesis and then promoting thrombotic diseases." (PMID 32748835, 2020).
Autoimmunity (7 papers, 2019 to 2026). The occurrence of an immune reaction against the organism's own cells or tissues. "However, recent reports of PNH arising in the setting of a CALR-mutated MPN,CML and a relapse of AML associated with TET2 and JAK2 mutations raise the question of whether autoimmunity is necessary in all cases." (PMID 31453016, 2019). "Our lab has successfully employed JAK1/JAK2 inhibitors to reverse established autoimmunity in NOD mice." (PMID 35606820, 2022). "Extensive research has confirmed the pathological roles of the IL-6/JAK2/STAT1/3 signaling pathway in inflammation, autoimmunity, and cancer, as well as its involvement in the pathogenesis of various rheumatic diseases." (PMID 40170729, 2025). "These inhibitors specifically target γc chain receptor signaling while sparing the signaling pathways of immunoregulatory cytokines, such as IL-10R (TYK2/JAK1), IL-27R (JAK1/JAK2), and IL-35R (JAK1/JAK2), which may contribute to preventing autoimmunity in the hair follicle." (PMID 41488086, 2025).
brain tumor (7 papers, 2017 to 2022). "JAK2 inhibitors were also shown to improve the survival of mice orthotopically xenografted with patient GBM brain tumor‐initiating cells and treated with TMZ." (PMID 33960104, 2022). "Here, we evaluated the preclinical efficacy of pacritinib, a novel compound targeting JAK2, using a collection of diverse patient-derived brain tumor initiating cells (BTICs)." (PMID 29253028, 2017). "TG02 is an inhibitor of CDKs, JAK2 and FLT3 able to penetrate the blood-brain barrier and is therefore an interesting therapeutic for brain tumors." (PMID 33918704, 2021). "Cucurbitacin-I and WP1066 administration or shRNA knockdown resulted in on-target JAK2/STAT3 inhibition and dramatically reduced GBM-derived Brain tumor stem cells." (PMID 29423098, 2018).
cerebral infarction (7 papers, 2017 to 2025). An ischemic condition of the brain, producing a persistent focal neurological deficit in the area of distribution of the cerebral arteries. "Resveratrol improves neurological function and alleviates neurological damage in cerebral infarction, inhibits apoptosis, and protects hippocampal neurons from damage induced by I/R injury via activation of the Janus kinase 2 (JAK2)/PI3K/AKT/mTOR pathway." (PMID 35712089, 2022). "The introduction of the Jak2 inhibitor AG490 blocked IL-6/Jak2 signaling, resulting in the amelioration of the poststroke neurological deficit, brain infarction, brain edema, oxidative stress, pro-inflammatory cytokine expression, and caspase-3 activation." (PMID 34943061, 2021). "BHD significantly improves the proliferation and differentiation of NSCs, cerebral infarction, and neuron viability, and decreases cell apoptosis via activation of the PI3K/AKT/Bad and Jak2/Stat3/Cyclin D1 pathways." (PMID 35712089, 2022). "Pretreatment with Jak2 inhibitor AG490 ameliorated neurological deficit, brain infarction, edema, oxidative stress, inflammation, caspase-3 activation, and Zonula Occludens-1 (ZO-1) reduction." (PMID 34943061, 2021).
chronic kidney disease (7 papers, 2017 to 2024). Impairment of the renal function secondary to chronic kidney damage persisting for three or more months. "Association with TTT remained significant independently of JAK2 mutation, white blood cell count and chronic kidney disease." (PMID 37143717, 2023). "Nevertheless, prognostic properties of higher ePVS regarding thrombosis are present independently of other predictors of higher thrombotic risk in PMF patients like chronic kidney disease, presence of JAK2 mutation, and higher WBC." (PMID 37143717, 2023). "Furthermore, research has shown that Chinese medicine can reduce proteinuria in mice with chronic renal failure by inhibiting the JAK2/STAT3 and PI3K/AKT signaling pathways." (PMID 40046619, 2024). "Our findings indicate that HGF may have protective effects in AOPP-mediated damage in chronic renal failure by keeping the balance of AGE receptor through regulating the JAK2/STAT3 signaling pathway." (PMID 28465704, 2017).
graft versus host disease (7 papers, 2020 to 2025). An immune system disorder that occurs after allogeneic hematopoietic stem cell transplant and is a reaction of donor immune cells against host tissues. "JAK2-deficient T cells are skewed towards Th2 and Treg polarization resulting in reduced graft versus host disease (GvHD)." (PMID 34073410, 2021). "As previously reported, JAK2, as a key modulator of the immune response, is involved in the occurrence of graft-versus-host disease, a contributor to transplant-related mortality following allogeneic hematopoietic cell transplantation." (PMID 35710633, 2022). "In addition, the recipient and donor JAK2 46/1 haplotypes were unfolded to be accountable for acute graft-versus-host disease after allogeneic hematopoietic stem cell transplantation." (PMID 35710633, 2022). "For instance, in graft-versus-host disease, SOCS1 regulates the inflammatory response by suppressing T-cell activation via inhibition of the CSF3R/JAK2/STAT3 signaling pathway." (PMID 40918404, 2025).
head and neck cancer (7 papers, 2013 to 2023). A primary or metastatic malignant neoplasm affecting the head and neck. "PD-L1 upregulation was JAK2/STAT1-dependent in head and neck cancer with wild-type EGFR, whereas JAK2 inhibition resulted in both basal and EGF-mediated downregulation of PD-L1." (PMID 29765155, 2018). "Intriguingly, erlotinib not only inhibited JAK2 phosphorylation but also significantly reduced PTPMeg2 expression level in head and neck cancer cells." (PMID 24019973, 2013). "Overexpression of EGFR is correlated with PD-L1 expression in head and neck cancers in a JAK2/STAT1-dependent manner, indicating a novel role for JAK2/STAT1 in EGFR-induced immune evasion." (PMID 31775797, 2019).
Myocardial fibrosis (7 papers, 2021 to 2025). "Taken together, the JAK2/STAT3 pathway promotes myocardial fibrosis by promoting inflammatory responses, inducing differentiation of myofibroblasts, and transmitting the apoptotic effects of TGF-β." (PMID 40881586, 2025). "Aberrant JAK2/STAT3 signaling has been linked to enhanced fibroblast transformation, potentially leading to myocardial fibrosis and exacerbating cardiac dilatation and dysfunction." (PMID 40290189, 2025). "Additionally, myocardial fibrosis is one of the typical pathological alterations of HCM, and PKM2 can also be involved in promoting cardiac fibrosis via mechanisms such as JAK2/STAT3 signal activation." (PMID 40271123, 2025). "The JAK2/STAT3 pathway is activated by the binding of inflammatory cytokines, such as IL-6, to its specific receptor and stimulates the expression of cytokines, such as IL-6, thereby increasing the inflammatory response and promoting myocardial fibrosis." (PMID 40881586, 2025). "In addition, TGF-β/Smad signaling pathway, JAK2/STAT3 signaling pathway, and P38 MAPK signaling pathway also play important roles in myocardial fibrosis." (PMID 40881586, 2025). "Thus, m6A modification may represent a potential therapeutic target for controlling myocardial fibrosis and improving outcomes in DCM, given its impact on the JAK2/STAT3 pathway." (PMID 40290189, 2025). "Similarly, TG-101348 or JSI-124, the specific inhibitor of JAK2, could also mitigate the myocardial fibrosis induced by hypoxia, but the vehicle has no such effects." (PMID 34764873, 2021).
tuberculosis (7 papers, 2012 to 2026). A chronic, recurrent infection caused by the bacterium Mycobacterium tuberculosis. "Baricitinib, a selective JAK1 and JAK2 inhibitor, may predispose to tuberculosis by suppressing interferon-gamma (IFN-γ)-mediated signaling, which is essential for macrophage activation and granuloma maintenance." (PMID 40735451, 2025). "In a recent report, the genes coding for IL-1β, TNF, IL-6, and JAK2 accounted for four of the seven most influential hub genes in the host response to tuberculosis disease." (PMID 36059986, 2022). "‘Tuberculosis’ KEGG pathway map comprised five signal transduction mediators, Irak2, Jak2, Malt1, Ripk2, and Src, regulated by induced enhancers." (PMID 30669987, 2019). "In an anti-tuberculosis drug-induced liver injury rat model, pyrrolidine dithiocarbamate effectively decreased the serum level of cytokines (TNF-α, IL-1β, and IL-6) by repressing the phosphorylation of JAK2 and STAT3." (PMID 38543164, 2024).
ankylosing spondylitis (6 papers, 2018 to 2024). An autoimmune chronic inflammatory disorder characterized by inflammation in the vertebral joints of the spine and sacroiliac joints. "IL-17A, which is the most abundant cytokine in ankylosing spondylitis sera and synovial fluid, enhanced osteoblast activity by increasing phosphorylated JAK2 (p-JAK2), total JAK2, and phospho-STAT3 (Tyr705) signalling." (PMID 35879773, 2022).
B-cell acute lymphoblastic leukemia (6 papers, 2013 to 2026). A neoplasm of lymphoblasts committed to the B-cell lineage, typically composed of small to medium-sized blast cells. "Activating JAK2 point mutations are implicated in the pathogenesis of myeloid and lymphoid malignancies, including high-risk B-cell acute lymphoblastic leukemia (B-ALL)." (PMID 29907650, 2018).
chronic GVHD (6 papers, 2020 to 2025). "Central to this evolution is the emergence of JAK2 inhibition, with ruxolitinib now firmly established as a standard of care for steroid-refractory acute and chronic GVHD." (PMID 40722603, 2025). "Ruxolitinib is a selective JAK1/JAK2 inhibitor, that has been recommended as a primary treatment in steroid-refractory chronic GVHD." (PMID 39478870, 2024). "The JAK2 V617F levels started to increase 10 years post-transplant with ongoing chronic GVHD and a corresponding decrease in donor chimerism levels." (PMID 37744628, 2023). "Recently the JAK-1 and JAK-2 inhibitor ruxolitinib has shown activity for the treatment of corticosteroid-refractory acute and chronic GVHD." (PMID 34691059, 2021). "6.5 years after HCT he is suffering from NIH grade 2 chronic GVHD and is now treated with a JAK2 inhibitor, but from his last follow up he scored Lansky 100%." (PMID 33193339, 2020). "Three patients are alive and well and one patient is suffering from moderate chronic GVHD with obstructive bronchiolitis but responded to Jak-2 inhibition." (PMID 33193339, 2020). "Recent clinical studies showed that downstream signaling of IL-6R via JAK2/STAT reduced acute and chronic GVHD in patients." (PMID 34691059, 2021).
diffuse large B-cell lymphoma (6 papers, 2017 to 2025). "In addition, the expression of PARP9 is regulated by the IFNγ-JAK2/STAT1-IRF1 signaling axis that is required for cancer cell survival in diffuse large B-cell lymphoma (DLBCL) with an active host inflammatory response." (PMID 34725336, 2021). "Diffuse large B-cell lymphoma (DLBCL) cells also produce IL-10 to induce PD-L1 expression on DLBCL cells through the activation of the JAK2/STAT3 pathway." (PMID 34063096, 2021).
hereditary thrombocytosis (6 papers, 2013 to 2025). "Cases of hereditary thrombocytosis associated with some germline JAK2 variants indicate a distinct impact of JAK2 variants compared to somatic JAK2 mutations." (PMID 40841769, 2025). "Rarely, uncommon JAK2 germline mutations cause hereditary thrombocytosis resistant to JAK2 inhibitors." (PMID 35205715, 2022). "Pathogenic JAK2 variants can cause a type of hereditary thrombocythemia with autosomal dominant inheritance." (PMID 34946900, 2021). "Other missense variants (p.Pro106Leu and p.Arg102Pro) have been described as germline mutations affecting the MPL/JAK2 signaling axis in hereditary thrombocytosis." (PMID 33533142, 2021). "Thus, all the molecules of the TPO/MPL/JAK2 signaling axis are likely to be involved in the MK hyperplasia associated with hereditary thrombocytosis and sporadic classical MPNs." (PMID 28955303, 2017). "In line with our finding, JAK2 germline mutations with a kinase activity lower than JAK2V617F and a specific activation of STAT1 were identified in hereditary thrombocytosis." (PMID 24066127, 2013).
influenza (6 papers, 2014 to 2026). An acute viral infection of the respiratory tract, occurring in isolated cases, in epidemics, or in pandemics; it is caused by serologically different strains of viruses (influenzaviruses) designated A, B, and C, has a 3-day incubation period, and usually lasts for 3 to 10 days. "Similarly, IL-6 plays an important role in the cytokine storm via the JAK2/STAT3 pathway in viral and bacterial pneumonia and is a predictive marker of inflammation indicative for a poor prognosis of influenza patients." (PMID 38791439, 2024).
injury (6 papers, 2020 to 2024). Damage inflicted on the body as the direct or indirect result of an external force, with or without disruption of structural continuity. "Moreover, lestaurtinib, a janus kinase and fms-like tyrosine kinase 3 (FLT3) inhibitor, was shown to attenuate acute lung injury by reducing neutrophil infiltration, which may also attenuate brain edema by inhibiting the JAK2/STAT3 pathway." (PMID 37234258, 2023). "The JAK2/STAT3 signaling pathway had been reported in oxidative damage of testis in mice, and it was also reported in ER stress in rat heart ischemia/reperfusion injury." (PMID 34582743, 2022).